CHCHD7 (coiled-coil-helix-coiled-coil-helix domain containing 7)
Synonyms: MGC2217; COX23
Tractability: PROTAC: its protein half-life has been measured.
Gene: Protein-coding gene on chromosome 8 (56,211,686 to 56,218,809, forward strand). Ensembl gene ENSG00000170791.
Subcellular location: Mitochondrion intermembrane space
Subcellular location (Human Protein Atlas): Cell Junctions; Aggresome
Pathways (Reactome):
Protein localization: Mitochondrial protein import
Gene Ontology:
Biological process: mitochondrial respiratory chain complex assembly
Cellular component: mitochondrion; mitochondrial intermembrane space
Genetic constraint (gnomAD): Loss-of-function variants: 6 observed, 5.4 expected, observed/expected ratio (o/e) 1.11, 90% interval 0.59 to 1.84. That is too few expected variants to judge how well the gene tolerates losing a copy. Missense variants: 38 observed, 41.15 expected, observed/expected ratio (o/e) 0.92, 90% interval 0.71 to 1.21. Synonymous variants: 15 observed, 14.52 expected, observed/expected ratio (o/e) 1.03, 90% interval 0.69 to 1.58.
Homologues: Orthologues: chimpanzee CHCHD7 (100% identical), macaque CHCHD7 (86% identical), mouse Chchd7 (82% identical), rat Chchd7 (82% identical), dog CHCHD7 (81% identical), guinea pig CHCHD7 (81% identical), tropical clawed frog chchd7 (53% identical), zebrafish chchd7 (52% identical).
Diseases named in the same sentence as CHCHD7 in open-access papers:
CHCHD7 is named in the same sentence as 3 diseases in open-access papers, as found by Europe PMC text mining. Sharing a sentence is not in itself a finding about the gene and the disease.
CHCHD7 shares sentences with these, for which no sentence is quoted: cancer (4 papers); lung adenocarcinoma (1); tumor (1).